KIT (KIT proto-oncogene, receptor tyrosine kinase)
Diseases named in the same sentence as KIT in open-access papers (continued):
Sharing a sentence is not in itself a finding about the gene and the disease.
gastrointestinal stromal tumor (continued). "The patient was submitted to a genomic study from leukocytes, confirming mutation in exon 11 of the KIT-gene Other studies of patients with dysphagia and gastrointestinal stromal tumors or mast or melanocyte disorders linked with the c-KIT mutation have been reported." (PMID 34064058, 2021). "The discovery of constitutive activating mutations in the proto-oncogene receptor tyrosine kinase (KIT) or platelet-derived growth factor receptor α (PDGFRA) oncogenes as molecular drivers of most gastrointestinal stromal tumors (GISTs) has radically changed our knowledge on their tumor biology." (PMID 33673554, 2021). "Well established examples include KIT mutations which are present in ~ 85% of gastro-intestinal stromal tumors, EGFR mutations that have been identified in ~ 15% of non-small cell lung cancers, and lung and colorectal cancers with mutations in the KRAS oncogene." (PMID 32087721, 2020). "Gastrointestinal stromal tumors (GISTs) originating from the interstitial cells of Cajal are mesenchymal tumors of the gastrointestinal tract and have been found to harbor c-KIT mutations and KIT (CD117) expression since 1998." (PMID 31100836, 2019). "KIT mutations are actionable in gastrointestinal stromal tumors (OncoKB level 1)." (PMID 30442178, 2018). "The overexpression or mutation of c-KIT is identified in many diseases, including cancer such as hematopoitic malignancy, prostate, adenocarcinoma lung cancers, pancreatic cancers, seminomas, melanoma, or gastrointestinal stromal tumors (GIST)." (PMID 29747481, 2018). "However, this study, which focused only on first-line treatment, included patients diagnosed before the identification of the KIT mutation in gastrointestinal stromal tumors." (PMID 28391775, 2017). "Gastrointestinal stromal tumors (GISTs) have activating KIT or PDGFRA gene mutations." (PMID 23408993, 2013). "In addition, somatic activating KIT mutations are associated with several cancers, including human gastrointestinal stromal tumors and human melanomas." (PMID 23555311, 2013). "Activating mutations of KIT were found in 88,2% (n = 127) of gastrointestinal stromal tumors (GISTs) and showed a significantly higher partial response rate to imatinib for exon 11 KIT mutation (83.5%) compared to exon 9 KIT mutation (47.8%) or no found mutation (0.0%)." (PMID 23476782, 2013). "Gastrointestinal stromal tumors (GISTs) in adults are generally driven by somatic gain-of-function mutations in KIT or PDGFRA, and biological therapies targeted to these receptor tyrosine kinases comprise part of the treatment regimen for metastatic and inoperable GISTs." (PMID 23730622, 2013). "The first is characterized by a single recurrent genetic aberration, such as somatic mutations of the v-kit Hardy-Zuckerman 4 feline sarcoma viral oncogene homolog (KIT) proto-oncogene in gastrointestinal stromal tumors or chromosomal translocations causing fusion genes." (PMID 24216705, 2013). "In gastrointestinal stromal tumors, myeloid leukemias and mast cell disorders, for example, c-KIT gene gain-of-function mutations result in constitutive tyrosine kinase activity and are considered to play a central role in oncogenesis and sustained tumor growth." (PMID 22839358, 2012). "The discovery of underlying molecular genetic abnormalities in gastrointestinal stromal tumors (GISTs) such as activating mutations in the tyrosine kinase genes, KIT and platelet derived growth factor receptor-alpha (PDGFRA), has led to remarkable clinical advances in treatment." (PMID 23036227, 2012). "Most gastrointestinal stromal tumors exhibit mutations in exon 11 of the KIT gene." (PMID 21171987, 2010). "KIT exon 11 mutations are observed in 60% of gastrointestinal stromal tumours (GIST)." (PMID 19536093, 2009). "It has been reported KIT mutation occurred in several solid cancers, including thymic cancer, breast cancer and gastrointestinal stromal tumor (GIST)." (PMID 41557053, 2026).
gastrointestinal stromal tumor (continued). "Rationale: Gastrointestinal stromal tumors (GIST), the most common mesenchymal tumors of the gastrointestinal tract, are primarily driven by activating mutations in the KIT intracellular segment." (PMID 40963922, 2025). "KIT is also a well-established therapeutic target in gastrointestinal stromal tumors (GIST), where activating mutations drive disease pathogenesis and predict robust responses to tyrosine kinase inhibitors (TKI) such as imatinib." (PMID 41301010, 2025). "While KIT is often mutated in gastrointestinal stromal tumors (GIST), which represents a targetable mutation with clinical benefit, it is rare in LMS, with mutations occurring in 1.8% of our cohort." (PMID 41228336, 2025). "Approximately 75% of patients with gastrointestinal stromal tumors (GIST) harbor functional mutations in KIT." (PMID 39749199, 2024). "Interestingly, KIT mutation is enriched in gastrointestinal stromal tumors (p = 7.28 × 10−5)." (PMID 37414794, 2023). "Most gastrointestinal stromal tumors (GIST) are driven by activating mutations in Proto-oncogene c-KIT (KIT) or PDGFRA receptor tyrosine kinases (RTK)." (PMID 37315115, 2023). "Mutations in JM domain of KIT in gastrointestinal stromal tumors (GIST) demonstrated a similar activation mechanism." (PMID 38071343, 2023). "Familial gastrointestinal stromal tumor (GIST) is a rare autosomal dominant genetic disorder associated with KIT and PDGFRA germline mutations." (PMID 35320498, 2022). "KIT mutations have been reported in more than 90% of cases of mast cytosis, 80–85% of cases of gastrointestinal stromal tumor (GIST), 10–20% of cases of melanoma, and cases of acute myeloid leukemia (AML), especially in core-binding factor (CBF) leukemia." (PMID 35563085, 2022). "Examples include c-KIT mutations in gastrointestinal stromal tumors (GIST) and the BCR-ABL translocation in chronic myelogenous leukemia (CML)." (PMID 35211401, 2022). "Some examples include EWSR1 gene rearrangement in Ewing sarcoma, MDM2 gene amplification in well-differentiated and dedifferentiated liposarcoma, and c-KIT gene mutations in gastrointestinal stromal tumor (GIST)." (PMID 33802620, 2021). "The majority of gastrointestinal stromal tumor (GIST) patients develop resistance to the first-line KIT inhibitor, imatinib mesylate (IM), through acquisition of secondary mutations in KIT or bypass signaling pathway activation." (PMID 34359600, 2021). "Gain-of-function mutations of the GFR KIT or PDGF-Rα drive gastrointestinal stromal tumor (GIST) progression." (PMID 34294128, 2021). "The majority of gastrointestinal stromal tumors (GIST) harbor an activating mutation in either the KIT or PDGFRA receptor tyrosine kinases." (PMID 34322383, 2021). "SDH-deficient gastrointestinal stromal tumors (GIST) account for 20–40% of all KIT/PDGFRA-negative GIST." (PMID 35059314, 2021). "Over 85% of gastrointestinal stromal tumors (GIST) are driven by oncogenic mutations of the genes encoding KIT and/or platelet-derived growth factor receptor A (PDGFRA) receptor tyrosine kinases." (PMID 33740926, 2021). "A gastrointestinal stromal tumor (GIST), the most common sarcoma, is most often driven by oncogenic KIT or PDGFRA mutations." (PMID 33568624, 2021). "Activating mutations in KIT/PDGFRA receptor tyrosine kinases drive gastrointestinal stromal tumors (GIST)." (PMID 34324512, 2021). "SDH-deficient gastrointestinal stromal tumors (GIST) account for 20–40% of all KIT/PDGFRA-negative GIST and are due to mutations in one of the four SDH-complex subunits, with SDHA mutations as the most frequent." (PMID 35059314, 2021). "Besides, ICC are the progenitor cells of gastrointestinal stromal tumors (GISTs), and a gain-of-function mutation of the c-KIT may lead to these tumors." (PMID 34064058, 2021). "Gastrointestinal stromal tumors (GIST) are common mesenchymal tumors, and their effective treatment depends upon the mutational subtype of the KIT/PDGFRA genes." (PMID 34830948, 2021).
gastrointestinal stromal tumor (continued). "Gain-of-function type KIT mutations are observed in other malignancies, such as gastrointestinal stromal tumor (GIST), seminoma, and acute myelogenous leukemia (AML), though the mutated sites are varied among these malignancies." (PMID 32023940, 2020). "Furthermore, the drug repurposing approach is even more applicable for STS with oncogenic mutations: gastrointestinal stromal tumors (GIST) with activating mutations in c-KIT, PDGFA and BRAF, myxoid round cell liposarcoma with activating mutation in PI3K/Akt signaling component PI3CA." (PMID 32317857, 2020). "In veterinary oncology, feline and canine mast cell tumor and gastrointestinal stromal tumor (GIST) frequently have KIT activating mutations and respond to Imatinib." (PMID 29385676, 2018). "Mutations in KIT are mostly found in leukemia, gastrointestinal stromal tumors (GIST), testicular germ cell tumor (TGCT) and melanoma." (PMID 29455662, 2018). "Gastrointestinal stromal tumors (GISTs), the most common mesenchymal tumors of the gastrointestinal tract, result from constitutively activating mutations in two oncogenes from the receptor tyrosine kinase family, KIT or platelet-derived growth factor receptor-α (PDGFRA)." (PMID 28402935, 2017). "Oncogenic mutations in KIT occur in 75-80% of gastrointestinal stromal tumors (GIST) and in 20-25% in PDGFRA." (PMID 29312620, 2017). "Gastrointestinal stromal tumors (GIST) arise within the interstitial cell of Cajal (ICC) lineage due to activating KIT/PDGFRA mutations." (PMID 27793025, 2016). "About 10–15% of adult, and most pediatric, gastrointestinal stromal tumors (GIST) lack mutations in KIT, PDGFRA, SDHx, or RAS pathway components (KRAS, BRAF, NF1)." (PMID 27974047, 2016). "Gastrointestinal stromal tumors (GIST) characteristically harbor in 85% of cases activating mutations in KIT or PDGFRA genes which encode a tyrosine kinase receptor." (PMID 27896638, 2016). "Effective small molecule targeted therapies have been established only in a small subset of this group with defined molecular backgrounds, such as imatinib for mutated KIT in gastrointestinal stromal tumors (GIST)." (PMID 26918731, 2016). "Gastrointestinal stromal tumors (GISTs) are characterized by mutations of KIT (v-kit Hardy-Zuckerman 4 feline sarcoma viral oncogene homolog) or PDGFRA (platelet-derived growth factor receptor α) that may be efficiently targeted by tyrosine kinase inhibitors (TKI)." (PMID 26867653, 2016). "Gastrointestinal stromal tumors (GIST) are the most common mesenchymal tumors of the gastrointestinal tract and are characterized by activating mutations of the receptor tyrosine kinases KIT or PDGFRA." (PMID 25781619, 2015). "Patients treated with imatinib for gastrointestinal stromal tumor (GIST) with c-KIT mutations in exon 11 have an 83.5% response rate versus 47.8% in patients with exon 9 mutations, and PIK3CA H1047R mutations may be more sensitive to PI3K/Akt/mTor inhibitors than other PIK3CA mutations." (PMID 26418953, 2015). "Given evidence that certain susceptibility loci and carcinogens are associated with characteristic mutations in other cancers, we hypothesized that these signature KIT or PDGFRA mutations may be similarly fundamental to understanding gastrointestinal stromal tumor etiology." (PMID 24159917, 2013). "[18 F]FDG-PET could also be a surrogate marker for the efficacy of erlotinib, another EGFR-TKI, in preclinical human head and neck carcinoma models and of the c-KIT inhibitor, imatinib, in models with activating c-KIT mutations in gastrointestinal stromal tumors (GISTs)." (PMID 24041012, 2013). "TKIs are used in first-line for chronic and acute myeloid leukemia (CML and AML) with BCR/ABL overexpression as well as for gastrointestinal stromal tumors (GIST) with c-KIT mutations." (PMID 23316191, 2012).
gastrointestinal stromal tumor (continued). "The majority of gastrointestinal stromal tumors (GIST) harbor gain-of-function mutations in KIT or PDGFRA, resulting in the activation of the downstream pathways PI3K/AKT, Ras/MAPK, and JAK/STAT3, and playing a crucial role in tumorigenesis." (PMID 22974104, 2012). "Oncogenic point mutations in KIT or PDGFRA are recognized as the primary events responsible for the pathogenesis of most gastrointestinal stromal tumors (GIST), but additional genomic alterations are frequent and presumably required for tumor progression." (PMID 20470368, 2010). "In addition, gain-of-function mutations in KIT, that is mutations that cause constitutive activation of the tyrosine kinase (TK), have been implicated in a variety of neoplasms including, gastrointestinal stromal tumours (GIST), mastocytosis, acute leukaemias, melanomas and other cancers." (PMID 19789626, 2009). "Similarly, arterial‐ and venous‐phase CECT radiomics can robustly predict KIT exon 9 mutation in gastrointestinal stromal tumors (GIST), underscoring the generalizability of combined multiphase imaging." (PMID 41583907, 2026). "Beyond CML, imatinib demonstrated substantial clinical efficacy in gastrointestinal stromal tumors (GIST), which frequently harbor activating mutations in c-KIT or PDGFRA that lead to ligand-independent receptor activation and oncogenic signaling." (PMID 41302945, 2025). "Recently, targeted therapies focused on molecular features were implemented in clinical practice, particularly for gastrointestinal stromal tumors (GISTs), characterized by the hyperactivity of c-KIT and PDFRα receptors." (PMID 40723917, 2025). "The membrane receptor tyrosine kinase KIT is the primary oncoprotein of gastrointestinal stromal tumours (GISTs)." (PMID 39981588, 2025). "There is additional evidence that AMPD3 is positively correlated with the receptor tyrosine kinase KIT in gastrointestinal stromal tumors, leading to drug resistance." (PMID 41256734, 2025). "Most gastrointestinal stromal tumours (GISTs) are driven by KIT proto‐oncogene, receptor tyrosine kinase (KIT)." (PMID 39981588, 2025). "CD117 (c-KIT), while also positive in this case, is less specific and can be expressed in a range of neoplasms, including gastrointestinal stromal tumors, seminomas and some melanomas." (PMID 40900681, 2025). "Gastrointestinal stromal tumors (GIST) are the most common mesenchymal tumors of the gastrointestinal tract, primarily driven by mutations in the KIT (∼80%)and Platelet-Derived Growth Factor Receptor Alpha (PDGFRA) (∼5%–10%) genes." (PMID 40170718, 2025). "Variants in KIT and PDGFRA also point to a possible link between familial gastrointestinal stromal tumours and CRC." (PMID 40627234, 2025). "In STS, however, actionable mutations are relatively rare, with the notable exception of KIT or PDGFRA alterations in gastrointestinal stromal tumors." (PMID 41228245, 2025). "Gastrointestinal stromal tumors (GISTs) are the predominant mesenchymal tumors within the gastrointestinal tract, primarily driven bymutations in the c-KIT or PDGFRα genes." (PMID 39917203, 2024). "KIT is required for the normal growth and differentiation of ICC, but excessive KIT triggers gastrointestinal stromal tumor." (PMID 38396943, 2024). "Genome-wide functional screening identifies CDC37 as a crucial HSP90-cofactor for KIT oncogenic expression in gastrointestinal stromal tumors." (PMID 38414063, 2024). "In medicinal chemistry and drug discovery, KIT(c-Kit) is considered one of the key targets for the management of various types of cancer, including melanoma, gastrointestinal stromal tumors, small cell lung carcinomas and acute myeloid leukemia." (PMID 38280104, 2024). "Among soft-tissue cancers, this pathogenic variant is found in 12–20% of malignant peripheral nerve sheath tumors and estimated 3.5–13.5% of primary KIT/PDGFRA wild-type gastrointestinal stromal tumors." (PMID 39018206, 2024).
gastrointestinal stromal tumor (continued). "NTRK fusions are mutually exclusive and are uncommonly identified in a subset of KIT/PDGFRA wild-type gastrointestinal stromal tumors (GIST)." (PMID 38200576, 2024). "Typically, immunohistochemistry of gastrointestinal stromal tumors expresses the marker CD117 (KIT), while smooth muscle actin expression (1A4) is more frequent in stromal tumors of the small intestine." (PMID 39087153, 2024). "Imatinib is a TKI inhibitor primarily used in human chronic myeloid leukemia but also in gastrointestinal stromal tumors due to its inhibition of c-KIT, PDGFR, and ABL kinases." (PMID 39408717, 2024). "On the other hand, miR-144-3p has been identified as a component of KIT-related regulatory networks in human Gastrointestinal Stromal Tumors (GISTs), suggesting its potential role in regulating the expression of the KIT gene." (PMID 38791725, 2024). "Gastrointestinal stromal tumour (GIST) is the most frequent soft tissue sarcoma and is characterised by activating mutations in the receptor tyrosine kinases KIT or PDGFRA." (PMID 37622176, 2023). "FGF2-mediated activation of FGFR1 promotes resistance to EGFR inhibitors in lung cancer, FLT3 inhibitors in AML, and KIT inhibitors in gastrointestinal stromal tumors." (PMID 37598282, 2023). "Gastrointestinal stromal tumors (GIST) with KIT exon 11 deletions involving in codons 557–558 (KIT Δ557–558) exhibit higher proliferation rates and shorter disease-free survival times compared with GISTs with other KIT exon 11 mutations." (PMID 37377752, 2023). "Imatinib plasma trough concentrations are associated with efficacy for patients treated for advanced or metastatic KIT-positive gastrointestinal stromal tumours (GISTs)." (PMID 37296838, 2023). "Most gastrointestinal stromal tumors are caused by protein kinases, particularly wild-type and mutant platelet-derived growth factor receptor A (PDGFRA) and KIT (GIST)." (PMID 37631077, 2023). "gastrointestinal stromal tumors (GISTs) with KIT exon 11 deletions have more malignant clinical outcomes." (PMID 37645430, 2023). "Gastrointestinal stromal tumour (GIST) is the most common mesenchymal tumour specific to the gastrointestinal tract and is commonly characterized by activating mutations in the KIT or PDGFRA receptor tyrosine kinases." (PMID 36765536, 2023). "Gastrointestinal stromal tumor (GIST) is a class of mesenchymal neoplasms of the digestive tract, and most of them possess an activated mutation of KIT or platelet-derived growth factor receptor alpha (PDGFRA)." (PMID 37675227, 2023). "As KIT is a target in other tumor forms, most notably in gastrointestinal stromal tumors, this variation in tumor biology results in a definite difference in therapeutic approaches between TCs and thymomas." (PMID 37893096, 2023). "Activating mutations in c-KIT and PDGFRA genes are considered the key molecular drivers of human gastrointestinal stromal tumors pathogenesis and are used to predict the response to Receptor tyrosine kinase inhibitors." (PMID 35878393, 2022). "GISTs are heterogeneous tumors, including various molecular entities with usually mutually exclusive mutations of activated oncogenes, mainly KIT or platelet-derived growth factor-alpha (PDGFRA) mutations." (PMID 35646090, 2022). "c-KIT has been regarded as a promising therapeutic target against gastrointestinal stromal tumor (GIST)." (PMID 36612139, 2022). "Presently, gastrointestinal stromal tumors (GIST) are increasing rapidly worldwide, mostly due to mutations in KIT and PDGFRA genes." (PMID 35187038, 2022). "Ripretinib is a switch control KIT kinase inhibitor approved for treatment of adults with advanced gastrointestinal stromal tumors who received prior treatment with 3 or more kinase inhibitors, including imatinib." (PMID 35560823, 2022). "The ABL, KIT, and PDGFR inhibitor Imatinib was effective in treating gastrointestinal stromal tumor with KIT or PDGFR overexpression or mutation." (PMID 36733386, 2022).